CDH10 (cadherin 10)
Diseases named in the same sentence as CDH10 in open-access papers:
CDH10 is named in the same sentence as 37 diseases in open-access papers, as found by Europe PMC text mining. Sharing a sentence is not in itself a finding about the gene and the disease. The quoted sentences say what the papers report.
colorectal cancer (6 papers, 2016 to 2022). A primary or metastatic malignant neoplasm that affects the colon or rectum. "A second enhancer region adjacent to CDH10 (Cadherin 10, chr5:24276200-24285200, implicated in colorectal cancer) was identified as recurrently mutated in 15/54 samples." (PMID 33632293, 2021). "CDH10 is shown to be highly mutated in colorectal cancer and associated with better survival." (PMID 35664067, 2022). "Recurrent mutations in CDH10 have recently been reported in EGFR/KRAS/ALK mutation-negative lung adenocarcinoma in never-smokers and as a prognostic mutation signature in colorectal cancer." (PMID 27093186, 2016). "Similarly, CDH10 contains 20 nonsense and 319 missense mutations and, in agreement with our results, has previously been identified as a potential TSG in colorectal cancer and lung squamous cell carcinoma." (PMID 28841835, 2017).
breast carcinoma (5 papers, 2020 to 2024). "Apart from breast cancer, we demonstrated by pan-cancer analysis of TCGA patient expression database that loss of CDH10 was common in other cancer types." (PMID 32292512, 2020). "CDH10 transcript levels were therefore examined in breast cancer patients and it was found that higher CDH10 expression was associated with improved relapse-free survival." (PMID 32292512, 2020). "In cells grown in 3D, progestins regulate a group of breast cancer-associated genes that are also regulated in 2D including CDH10, PGR, CHEK2, LSP1, TERT, SDPR, but also a new set of 3D-exclusive genes, associated to the ECM including members of the integrin family, Laminins, and AKT3." (PMID 38565950, 2024). "In addition, the increased Cdh10 gene expression observed in stressful situations is associated with worse survival rates in breast cancer cases." (PMID 38929688, 2024). "We therefore investigated whether loss of CDH10 was common in breast cancer and other tumor types and whether this was associated with an increased EHMT2 expression." (PMID 32292512, 2020). "The prognostic power of CDH10 was further evaluated by investigating its association with relapse-free survival in the different breast cancer molecular subtypes, or intrinsic subtypes, Luminal A and Luminal B for the ER+ tumors and HER2+ and basal-like for the ER- tumors." (PMID 32292512, 2020). "We propose that CDH10 possesses a metastasis suppressive function in breast cancer and that G9a represents an attractive target for the treatment of hypoxia-driven metastatic breast cancer." (PMID 32292512, 2020). "Data presented in this part of our study suggest that CDH10 expression is therefore prognostic in breast cancer, notably in more aggressive ER- subtypes." (PMID 32292512, 2020). "Through gene expression profiling, we identified CDH10 to be an important G9a target that regulates breast cancer cell motility." (PMID 32292512, 2020). "We found that CDH10 is prognostic in breast cancer patients, with greater influence on the ER- subtype." (PMID 32292512, 2020). "The breast cancer samples were then further stratified into the different molecular subtypes and the expression ratios of tumor to normal tissue for CDH10 and EHMT2 were compared as previously." (PMID 32292512, 2020). "CDH10 overexpression significantly reduces cellular movements in breast cancer cell lines and prevents the hypoxia-mediated increase in cell motility." (PMID 32292512, 2020). "While CDH10 expression was prognostic in all the breast cancer subtypes analysed, the ER- subtypes HER2+ and basal-like were characterized by a stronger correlation." (PMID 32292512, 2020). "We also showed that CDH10 is able to reduce motility of breast cancer cells and attenuate the hypoxic response, suggesting that, at least partially, loss of CDH10 is responsible for the increased migratory potential observed during hypoxic stress." (PMID 32292512, 2020). "Collectively, our results demonstrate that inhibiting G9a activity reduces cellular motility and metastatic spread in breast cancer and promotes CDH10 expression under hypoxic conditions." (PMID 32292512, 2020). "The ability of EHMT2 and CDH10 mRNA to stratify breast cancer patients was analysed in the KM Plotter database." (PMID 32292512, 2020). "Publicly available databases were examined to evaluate the importance of G9a (EHMT2) and CDH10 expression in breast cancer." (PMID 32292512, 2020). "Collectively, these data support the possible role for CDH10 as an important factor modulating cell motility in breast cancer following exposure to hypoxia." (PMID 32292512, 2020). "However, when the mutational status was investigated in breast cancer patients using publicly available databases (through cBioportal), no significant frequency of gene alterations was identified for both EHMT2 and CDH10." (PMID 32292512, 2020). "Furthermore, CDH10 is a prognostic biomarker in breast cancer, especially in ER- subtype." (PMID 32292512, 2020).
breast carcinoma (continued). "In addition, we show that CDH10 expression is prognostic in breast cancer and that it is inversely correlated to EHMT2 (G9a) transcript levels in many tumor-types, including breast cancer." (PMID 32292512, 2020). "In addition, we demonstrate that CDH10 expression is associated with improved relapse‐free survival in breast cancer, indicating that CDH10 acts as a metastasis suppressor and its downregulation is an integral part of hypoxia-mediated EMT in breast cancer." (PMID 32292512, 2020).
lung carcinoma (5 papers, 2015 to 2025). "This is in contrast to lung cancer which was previously reported to be frequently associated with mutations on the CDH10 gene, where a significantly higher percentage of CDH10 alterations were detected." (PMID 32292512, 2020). "Somatic mutations in CDH10, expressed predominantly in the brain and involved in synaptic adhesions and axon growth and guidance, are associated with colorectal, gastric, and lung cancer and are considered driver mutations in pancreatic cancer." (PMID 40725113, 2025). "We additionally observed that the CDH10 site, which has been established as a tumor suppressor in lung cancer, was correlated with the increased presence of eRNA chrX." (PMID 34439379, 2021). "CDH10 has been proposed to act as a tumor suppressor in lung cancer, where its overexpression was shown to impact both the proliferative and motility potential of tumor cells." (PMID 32292512, 2020). "Overexpression of CDH10 significantly inhibited cell proliferation in wild-type mouse embryonic fibroblasts (MEFs) and mouse lung cancer cell line L793." (PMID 26503331, 2015). "In the functional assays using two lung cancer cell lines with high CDH10 expression (NCI-H522 and NCI-H1373), CDH10 silencing using different shRNAs consistently resulted in a significant increase in cell proliferation and soft-agar colony formation." (PMID 26503331, 2015).
autism (4 papers, 2014 to 2022). Persistent deficits in social interaction and communication and interaction as well as a markedly restricted repertoire of activity and interest as well as repetitive patterns of behavior. "In addition, a small cluster of the network showed co-expression of several genes (NRXN1, CACNA1A, CDH10, and others) associated with autism and/or epilepsy." (PMID 27358653, 2016). "Genetic studies shows an involvement of cadherin 10 (CDH10) and cadherin 9 (CDH9) in the pathogenesis of autism." (PMID 24756565, 2014).
autism spectrum disorder (4 papers, 2010 to 2024). A spectrum of developmental disorders that includes autism, and Asperger syndrome. "Furthermore, both CDH9 and CDH10 have been found associated with autism spectrum disorders (ASD), suggesting that genetic variations of these cadherins impair social behavior." (PMID 39570883, 2024). "Other genes such as CDH10, encoding neuronal cell–adhesion molecules, were already shown to be associated with neuropsychiatric disorders (e.g. autism spectrum disorders) but not specifically to schizophrenia so far." (PMID 38573526, 2024).
gastric cancer (4 papers, 2017 to 2024). A primary or metastatic malignant neoplasm involving the stomach. "Missense mutations at codon 400 in CDH1 and at codon 570 in CDH10 have been previously reported in gastric carcinoma (COSMIC IDs COSM1159626, COSM20771) and urinary tract carcinoma (COSM1311079), respectively." (PMID 29287594, 2017). "In addition, gastric cancer patients were likely to have mutations in CDH1, ACTRT1, GANAB, and CDH10 genes in the High-CCDC80 group." (PMID 38872096, 2024). "By analyzing gastric cancer (GC) patients in two independent cohorts, Luo and co-workers showed that cadherins CDH2, CDH6, CDH7 and CDH10 were significantly associated with a poor GC prognosis." (PMID 35631574, 2022).
lung squamous cell carcinoma (4 papers, 2015 to 2022). "CDH10 was found to be frequently mutated in both lung squamous cell carcinoma and adenocarcinoma than other cancer types, which further indicated the importance of CDH10 mutations in NSCLC development." (PMID 26503331, 2015).
pancreatic cancer (3 papers, 2021 to 2025). "Also, CDH10 is involved in sporadic pancreatic carcinogenesis, and might have a role in rare cases of familial pancreatic cancer." (PMID 38239411, 2023).
breast tumor (2 papers, 2020). "For examples, fibroblast-like synoviocytes can migrate and invade into pigmented villonodular synovitis by expressing CDH11 63, Silencing of CDH10 was also found as another mechanism to enhance breast tumor cell mobility in hypoxic conditions." (PMID 33204327, 2020).
glioma (2 papers, 2020 to 2021). A benign or malignant brain and spinal cord tumor that arises from glial cells (astrocytes, oligodendrocytes, ependymal cells). "On the contrary, CDH10 is largely expressed in glioma and its expression is higher in quiescent mouse neural stem cells compared with non-quiescent EGFR+ neural stem cells." (PMID 34885053, 2021). "In the other 6 cancer types (group 2: head and neck, prostate, glioma, cervical, glioblastoma and kidney chromophobe) CDH10 expression was lost or reduced, but this was not correlated with increased EHMT2 expression." (PMID 32292512, 2020).
pancreatic ductal adenocarcinoma (2 papers, 2020 to 2022). An infiltrating adenocarcinoma that arises from the epithelial cells of the pancreas. "Mutations in CDH10 that lead to a loss of expression are associated with pancreatic ductal adenocarcinoma and metastatic small-cell gallbladder neuroendocrine carcinoma 30,32." (PMID 32292512, 2020).
asthma (1 paper, 2023).
diabetes (1 paper, 2024). "In diabetes, CDH10 and the cadherin family were identified in several complications of diabetes mellitus such as diabetic peripheral neuropathy and diabetic kidney disease." (PMID 38573526, 2024).
endometrial cancer (1 paper, 2020). Primary or metastatic malignant neoplasm involving the endometrium (mucous membrane that lines the endometrial cavity). "However, the link between CDH10 and metastasis has not been extensively studied to date, with only one report of CDH10 mutation being frequent in metastatic endometrial cancer." (PMID 32292512, 2020).
ischemia (1 paper, 2021). A hypoperfusion of the BLOOD through an organ or tissue caused by a PATHOLOGIC CONSTRICTION or obstruction of its BLOOD VESSELS, or an absence of BLOOD CIRCULATION. "Under nonischemic conditions, pericytes expressed Cdh19, Cdh6, Cdh10, Cdh4, Cdh13, and Cdh5; after ischemia, the cadherin genes that were predominantly expressed were Cdh15, Cdh11, Cdh3, and Cdh2." (PMID 33726849, 2021).
kidney cancer (1 paper, 2020). Primary or metastatic malignant neoplasm involving the kidney. "In accordance with this model, CDH10 transcript levels in kidney cancers were found to be strongly reduced regardless of EHMT2 expression." (PMID 32292512, 2020). "In addition, kidney cancers clustered to the right end of groups 1 and 2, which for both groups corresponded to the lowest expression of EHMT2, as well as low CDH10 expression." (PMID 32292512, 2020).
metastatic disease (1 paper, 2020). "Finally, in order to understand whether G9a inhibition could regulate the expression of CDH10 in vivo, immunohistochemistry (IHC) analysis of CDH10 was performed on lung sections dissected from mice treated with UNC0642 following establishment of metastatic disease." (PMID 32292512, 2020).
myopia (1 paper, 2010). "Six candidate genes CDH6, CDH10, CDH12, PDZD2, GOLPH3, and ZFR at this high myopia locus were selected on the basis of their function to screen for gene mutations by re-sequencing." (PMID 21042559, 2010).
prostate carcinoma (1 paper, 2020). A carcinoma that arises from epithelial cells of the prostate gland. "Moreover, CDH10 was described to be prognostic in prostate cancer and its expression was found to be lost in aggressive forms of the disease 31,53." (PMID 32292512, 2020).
cancer (14 papers, 2007 to 2024). A tumor composed of atypical neoplastic, often pleomorphic cells that invade other tissues. "A number of recent studies have described a correlation between the loss of CDH10 expression and cancer." (PMID 32292512, 2020). "Mutations and loss of expression of CDH10 are associated with various cancers types 30,31,38." (PMID 32292512, 2020). "CDH10 reduces cancer cellular motility and loss of the protein may represent an important step in the hypoxia-mediated modulation of cellular motility." (PMID 32292512, 2020). "We speculate that the recurrent CDH10 mutations we detected in SCLC may perform similar roles as CDH1 mutations in other cancers to promote SCLC aggressiveness, leading to poor patient survival." (PMID 27093186, 2016). "CDH10 encodes a cadherin superfamily, integral membrane protein that mediates calcium-dependent cell-cell adhesion and might play a significant role in cancer progression and metastasis." (PMID 25112956, 2014). "This clinical data demonstrates a positive correlation to our mouse stress studies, linking stress to DNA methylated genes Cdh10 and Tbc1d9, related to cancer prognosis and survival." (PMID 35664067, 2022). "Consistent with this, expression of EHMT2 and CDH10 are inversely correlated in multiple cancer types." (PMID 32292512, 2020). "When the two ratios were compared with each other and tumors were ordered from the highest EHMT2:CDH10 ratio to the lowest, 9 out of 15 cancer types were characterised by a strong inverse correlation between the two genes." (PMID 32292512, 2020). "We also found copy number loss of cancer genes such as CCNE1, MAF, MAFB, MYC, ZNF479, and MGMT and copy number gain of FOXA2, CDH10, and GPC5 in at least two WDPM cases." (PMID 32545767, 2020). "Median expression of EHMT2 and CDH10 in tumors was compared with their respective expression in normal tissues and the two ratios were then compared with each other in each cancer type." (PMID 32292512, 2020). "Moreover, CDH10 overexpression was also able to reduce cell motility even in normoxic condition, supporting the role of CDH10 as an adhesion molecule that can inhibit cancer cell motility phenotype." (PMID 32292512, 2020). "Taking advantage of TCGA pan-cancer database, EHMT2 and CDH10 expression levels were obtained in cancers for which gene expression data was available for both normal and tumor tissues." (PMID 32292512, 2020). "Our results showed that the heat diffusion algorithm predicted 5 putative cancer gene CDH10, CHST11, GRM3, VAV1 and CCR4 from Tier 2 of the Cancer Gene Census6." (PMID 31500564, 2019). "This shows that CDH10 and TBC1D9 are important genes in cancer and stress." (PMID 35664067, 2022). "Cadherin-10 (CDH10), the type II classical cadherin, a protein binding molecule in terms of molecular function and is used as a biomarker in the prognosis of certain types of cancer, whilst CDSN is involved in skin immune-related disease." (PMID 32106598, 2020). "In addition to known cancer driver genes such as ERBB2 (6% of cases), NRAS (3%), MET (3%), PIK3CA (1%), AKT2 (1%), TSC1 (1%), and ERBB4 (1%), several putative cancer genes were identified, such as PTPRC, SYNE2, GRIN2A, and CDH10." (PMID 24576404, 2014).
tumor (9 papers, 2015 to 2024). "The majority of tumor types analysed displayed a loss of expression of CDH10 when compared to normal tissue expression levels." (PMID 32292512, 2020). "For CD8 + T cell, we found that the expression level of CDH10 (r = 0.183, P = 4.06 × 10−4) in GC tumor tissues were closely related to CD8 + T cell immune infiltration." (PMID 34880371, 2021). "Tumor immune infiltration abundance of macrophage also shown a significantly associated with CDH2 (r = 0.474, P = 3.59 × 10−22), CDH6 (r = 0.418, P = 4.20 × 10−17) and CDH10 (r = 0.492, P = 6.60 × 10−24) in GC tumor tissues." (PMID 34880371, 2021). "The expression level of CDH2(r = 0.263, P = 3.54 × 10−7), CDH6 (r = 0.307, P = 2.04 × 10−9) and CDH10 (r = 0.33, P = 9.99 × 10−11) in GC tumor tissues were closely related to CD4 + T cell immune infiltration." (PMID 34880371, 2021). "We uncovered a high somatic mutation frequency of the cell-cell adhesion/Wnt/Hippo pathway genes in lung SQCC and demonstrated that CDH10 exerted tumor suppressor role." (PMID 26503331, 2015). "The CDH10 mutation was reported to be significantly associated with better overall survival, independent of tumor–node–metastasis staging." (PMID 36139456, 2022). "All these four prognostic genes were significant associated with dendritic cell Tumor immune infiltration abundance: CDH2 (r = 0.296, P = 5.84 × 10−9), CDH6 (r = 0.164, P = 1.49 × 10−3), CDH6 (r = − 0.105, P = 4.41 × 10−2) and CDH10 (r = 0.274, P = 7.78 × 10−8)." (PMID 34880371, 2021). "Collectively, these functional studies further demonstrated that CDH10 might serve as a tumor suppressor in lung carcinogenesis." (PMID 26503331, 2015). "Several lines of evidence suggest that CDH10 potentially play a tumor-suppressor role." (PMID 26503331, 2015). "Tumor immune infiltration abundance of neutrophil were closely correlated with CDH2 (r = 0.149, P = 4.10 × 10−3) and CDH10 (r = 0.147, P = 4.54 × 10−3) expression." (PMID 34880371, 2021).
CDH10 also shares sentences with these, for which no sentence is quoted: lung adenocarcinoma (2 papers); adenocarcinoma (1); diabetic kidney disease (1); dyslexia (1); epilepsy (1); Fanconi anemia (1); gallstones (1); glioblastoma (1); graft versus host disease (1); kidney tumor (1); lung (1); schizophrenia (1); synovitis (1); systemic lupus erythematosus (1); type 1 diabetes mellitus (1); urinary tract carcinoma (1).